SOX2 (SRY-box transcription factor 2)
Diseases named in the same sentence as SOX2 in open-access papers (continued):
Sharing a sentence is not in itself a finding about the gene and the disease.
cancer (continued). "Compared to Sox2-negative FMCs, Sox2-positive carcinomas were associated with an almost 2-fold increased risk of distant metastasis over time (HR = 1.87, 95% CI 1.00–3.51, p = 0.0398)." (PMID 33553286, 2020). "However, another crucial function for Sox2 has recently emerged: its role in cancer development and promotion of CSCs characteristics." (PMID 31610800, 2019). "In addition, the levels of MTA3 in both samples from TSCC patients and TSCC cell lines were negatively correlated with SOX2, a key regulator of the plasticity of cancer stem cells (CSCs)." (PMID 31552166, 2019). "Moreover, we established the negative regulation of SOX2, a key regulator in the plasticity of cancer stemness, by MTA3 repressed the number of ALDH1-positive cells and cell proliferation in TSCC cells." (PMID 31552166, 2019). "SOX2 could be a potential therapeutic target to impede the progression of SOX2‐positive cancer cells or recurrence of androgen‐independent PCa." (PMID 30206982, 2019). "In agreement with previous reports regarding SOX2 roles in cancer cell proliferation and apoptosis, SOX2 knockdown by siRNA resulted in significant anti-proliferative and apoptosis-inducing effects in vitro as measured by CCK-8, BrdU incorporation and Annexin V-PI flow cytometric assays." (PMID 31399556, 2019). "Contrary to other organs, where somatic stem cells are shown to be able to become transformed into cancer stem cells, the roles of SOX2+ PSCs in tumourigenesis remain poorly understood, possibly due to the patchy knowledge of the pathways regulating SOX2+ PSC fate and proliferation." (PMID 30912742, 2019). "SOX2 could be a potential therapeutic target to thwart the progression of SOX2‐positive cancer cells or recurrence of androgen‐independent PCa." (PMID 30206982, 2019). "Sox2 encodes a high-mobility group (HMG) DNA-binding transcription factor with important roles in embryonic development, embryonic and adult neural progenitors, and the progression of many forms of cancer." (PMID 31124784, 2019). "SOX2 is reported as either oncogene or tumor suppressor gene in various cancer types." (PMID 31516388, 2019). "SOX2 (Sex-determining region Y box 2) also functions as an oncoprotein and promotes cancer progression but the mechanisms involved remain largely unknown." (PMID 30806068, 2019). "Further, stem cell-related genes OCT4 and SOX2 are among the target genes regulated by miR-145, suggesting that miR-145 may play an important role in the maintenance of cancer stem cells." (PMID 31771617, 2019). "SOX2 is a transcription factor that maintains the pluripotent properties of stem cells, and it is highly expressed in the cancer stem cells of breast, prostate, lung, uterine cervix, ovarian, and bladder cancers." (PMID 31619018, 2019). "Instead, we used TCGA data to determine whether high expression of SOX2 and GLI molecules is associated with more cancer relapse following gemcitabine treatment." (PMID 30382189, 2019). "SOX2 expression was more in TT lysates than the normal prostatic tissue (NT) lysates (lane 1), suggesting that expression of SOX2 may have a role in the progression of cancer." (PMID 30206982, 2019). "Collectively, these results suggest that SIX1 could play a widespread role in the regulation of SOX2-mediated stem phenotypes in cancer." (PMID 30723235, 2019). "Accumulating evidence suggests an important role for SOX2 in cancer immune evasion." (PMID 31080551, 2019). "p63 has been shown to co-bind common BSs with Sox2 in cancer cells, where they physically interact." (PMID 31296872, 2019). "When Colo-320 and MCF-7 cancer cell lines were cultured in ESC conditioned medium, they exhibited re-expression of pluripotency-associated markers, including Oct-4, NANOG, and SOX2 and reduction of tumorigenicity in vitro, indicating the successful reprogramming from malignancy into benignity." (PMID 31464654, 2019).
cancer (continued). "The direct link to SOX2 shown here identifies a novel mechanism by which SIX1 could contribute to self-renewal in cancer stem cells." (PMID 30723235, 2019). "In addition, key regulators of ESC identity, such as Oct4, Sox2 and Nanog, are frequently overexpressed in cancer stem cells derived from different types of cancers." (PMID 31891567, 2019). "This hypothesis is also supported by the fact that p63 and Sox2, which is functionally very similar to Sox3, bind a subset of common BSs and physically interact in cancer cells." (PMID 31296872, 2019). "Some meta-analyses investigated the prognostic value of CD133 and SOX2 expression in some human cancers, but the prognostic significance of CD133 and SOX2 expression in advanced cancer patients remains unclear and unknown." (PMID 30693028, 2019). "Subsequently, we suggest that SOX2 can be a direct downstream target of has-miR-590-3p indicating that it may have a role in the self-renewal and self-maintenance of cancer cells." (PMID 31781476, 2019). "The majority of studies showed that SOX2 overexpression may promote cancer progression; however, it has also been reported that SOX2 overexpression inhibits cell proliferation." (PMID 31640140, 2019). "Further study we found that Ezh2 could increase the population of cancer stem cells by regulating Nanog, Sox2, CD44." (PMID 30621625, 2019). "To further understand how DEGs were regulated, we analysed transcription factor (TF) binding using Enrichr and observed that DEGs were enriched for targets of TFs associated with self-renewal and cancer stem cell function (SUZ12, SOX2, REST, EZH2, SMAD4 and NANOG)." (PMID 31014368, 2019). "Recent findings have shown that ectoderm- and endoderm-derived tissues continue expressing stem-cells related transcription factors of the SOX-family of proteins such as SOX2 and SOX9 which have been implicated in the presence of cancer stem-like cells (CSCs) in tumors." (PMID 31057614, 2019). "Increased Oct-3/4 or Sox2 expressing cancer cells were observed during PDX passaging." (PMID 31126020, 2019). "Experiments demonstrated that miRNA-216a-5p interacted with DANCR and its inhibitor could weaken the influences induced by DANCR knockdown for cancer cells, including cell proliferation and invasion, and the expression of Nanog, SOX2, and OCT4." (PMID 30910842, 2019). "OCT4 and SOX2 are important transcriptional factors, and their expression has been reported to correlate with tumorigenesis, chemoresistance, and maintenance of the stem-cell-like phenotype in cancer cells, including CC cells." (PMID 31114449, 2019). "Furthermore, for the first time, we have developed and characterized a novel monoclonal antibody against Sox2 phosphorylation at T116 site, which can be used as a surrogate potential marker to identify more tumorigenic and cancer stem-like subpopulation in BC." (PMID 29401647, 2018). "Its expression increases theexpression of Nanog/Sox2/oct4 in cancers." (PMID 29308623, 2018). "On the other hand, Metformin was effective only in acidosis-exposed cancer cells, since its efficacy is significantly reduced in SOX2-silenced cells, even though a further cell death reduction could be expected." (PMID 30466459, 2018). "However, it is becoming increasingly apparent that ectopic expression and amplification of SOX2 was significantly correlated with cancer development." (PMID 30108202, 2018). "Gene Ontology (GO) analysis showed that downregulated genes (decreased greater than onefold relative to control) upon TP63 or SOX2 silencing were strongly enriched for cellular phenotypes important for cancer biology, including cell-cycle regulation, chromatin binding, and cell proliferation." (PMID 30190462, 2018). "The direct role of Sox2 in conferring cancer stemness has been nicely illustrated by many studies." (PMID 29401647, 2018).
cancer (continued). "To investigate whether TGFβ1 is capable of increasing NSCLC stem-like cell population, we measured mRNA expression level of cancer stem cell markers, including Oct4, Nanog, and Sox2, using real-time PCR." (PMID 29995950, 2018). "SOX2OT is over expressed in human cancer tissues of lung, esophagus and breast when comparing to normal and it’s over expression in tumors is associated with SOX2, which is located within SOX2OT." (PMID 30202240, 2018). "Studies show that SOX2 is frequently abnormally expressed in a variety of malignant tumors." (PMID 30186173, 2018). "As a stem cell transcription factor, SOX2 is important for the maintenance of pluripotent cells and may play a role in cancer." (PMID 29854282, 2018). "Importantly, TBX21 induces cancer stemness biomarker (SOX2 and OCT4) alteration in LUAD cells and the mice model which is consistent with the acquisition of CSC maintenance." (PMID 29615105, 2018). "In addition, SOX2, a transcription factor that controls tumor initiation and cancer stem-cell functions, can directly bind to the PD-L1 promoter and transactive its expression, contributing to the increased proliferation of hepatocellular carcinoma cells." (PMID 30283733, 2018). "Moreover, SOX2 was reported to promote tumorigenesis, progression, and metastasis in multiple types of cancer through controlling stem cell activity." (PMID 30108202, 2018). "Considering its nature of pluripotency, it is probable that Sox2 might be secondarily induced when CSCs produce the cancer tissue structures." (PMID 30518951, 2018). "Correlating with the biological importance of Sox2 in conferring cancer stemness and tumorigenecity in BC, multiple studies have shown that the protein expression of Sox2 detectable by immunohistochemistry significantly correlates with various clinicopathologic parameters." (PMID 29401647, 2018). "SOX2 is frequently up regulated in cancers and related with worse outcomes." (PMID 30186173, 2018). "Finally, a recent report indicates that the TF Sox2 which is transcriptionally repressed by p27 and p21 plays a key role in triggering tumor initiation and cancer-stem cells functions in squamous-cell carcinoma." (PMID 29899857, 2018). "HNSCC is the fourth cancer identified as having altered SOX2 expression (21%)." (PMID 29374236, 2018). "Furthermore, during ethanol‐induced cellular transformation, cells gained the phenotypes of cancer stem cells (CSCs) by expressing pluripotency maintaining factors (Oct4, Sox2, cMyc and KLF4) and stem cell markers (CD24, CD44 and CD133)." (PMID 29761897, 2018). "In this present study, we demonstrated that ALDH+ human OSCC cells are characterized by upregulated expression of the pluripotency transcription factors OCT4, Nanog and Sox2, as well as exhibit enhanced cancer stemness, as demonstrated by enhanced tumorsphere formation, in vitro." (PMID 30143678, 2018). "SOX2 expression has been reported at both the RNA and protein levels for many cancers." (PMID 28388544, 2017). "Therefore, not surprisingly, it has been suggested that targeting pluripotency transcription factors such as Nanog and SOX2 can be a promising strategy to solve the current therapeutic limitation on hard-to-treat cancer types such as GBM28." (PMID 28842598, 2017). "In addition, NG type cells had a significantly higher percentage of cancer stem cells that express CD133+ Sox2+ or AGR2+ BMI1+, and were more tolerant to treatment with the chemotherapeutic agents cisplatin and etoposide." (PMID 28736504, 2017). "In fact, several lines of evidence argue that SOX2 levels do rise during cancer." (PMID 28388544, 2017). "Sox2 is another important factor involved in regulation of putative cancer stem cells." (PMID 28404967, 2017). "Over the past 10 years, SOX2 has been shown to be expressed in at least 25 different cancers." (PMID 28388544, 2017). "In this review, we provide an overview of SOX2 in cancer and focus on two broad topics." (PMID 28388544, 2017).
cancer (continued). "Since Sox2 expression was always found in the rounded cells, we then analyzed whether rounded cells expressed putative cancer stem cell markers." (PMID 29228716, 2017). "We observed that cancer cells efficiently internalized hESCs-Exo, and that these exosomes contained both mRNA and proteins of specific hESCs pluripotency markers (i.e. SOX2, OCT4, NANOG, SSEA4)." (PMID 28068409, 2017). "The link between SOX2 and EMT in some cancers was shown by directly altering the levels of SOX2." (PMID 28388544, 2017). "This soon turned into an avalanche of studies examining SOX2 in human cancer." (PMID 28388544, 2017). "Importantly, even partial reductions in SOX2 levels have been reported to significantly decrease cell viability, clonal growth, sphere formation, and tumorigenicity in multiple cancer types." (PMID 28388544, 2017). "As the core pluripotency factors OCT4, SOX2 and c-Myc are regulated by lincRNAs feedback loops, it is therefore suggested that lincRNA may be involved in maintaining cancer stem cell phenotypes." (PMID 28102845, 2017). "However, additional work will be needed to determine which of these mechanisms are utilized in specific cancers to fine tune SOX2 expression and function." (PMID 28388544, 2017). "Additionally, to examine the effect of 2DG and metformin on cancer stem-like cells, we quantified the expression of genes associated with “stemness” including OCT-4, Nanog, Sox-2, ALDH1A, and c-Myc." (PMID 29100387, 2017). "Previously, we established a GSC-like sphere culture system in which SOX2 was expressed at significant levels and hypothesized that PPARγ ligands may affect cancer stemness and induce apoptosis in GBM." (PMID 28642874, 2017). "In addition, Wnt/β-catenin signaling keeps the stemness of cancer stem cells via up-regulating stem cell-related transcription factors Oct4, Sox2, c-Myc, Nanog and KLF4." (PMID 28350360, 2017). "Ultimately, the role of SOX2 in cancer cell biology and the formation of metastases remain unclear and require further studies." (PMID 28002801, 2017). "Although the anti-cancer agents fluorouracil and cisplatin suppressed the proliferation of miPS-LLCcm cells, these drugs did not alter the expression of stemness markers, including Nanog, SOX2, c-Myc, Oct3/4 and Klf4." (PMID 29228699, 2017). "Clearly, knockdown studies have established that SOX2 plays important roles in these cancers." (PMID 28388544, 2017). "The fact that drug removal reinstated migration could be possible since the brCSCs which survived Pax treatment differentiated into cancer cells, as evident by down regulation of SOX2, and promoted cell migration after Pax withdrawal." (PMID 28835684, 2017). "As mentioned, cancer growth and invasion are most probably due to the capacity of some cells in the tumor to conserve stemness characteristics, keeping high expression of Nanog, Oct4, Sox2 and c-Myc, all of which are TCF4/β-catenin targets." (PMID 29261132, 2017). "Following internalization, exosomes were able to transfer their cargo to target cancer cells and induce a dose-dependent increase in SOX2, OCT4 and Nanog proteins, with a concomitant dose-dependent decrease in the proliferation and increase in the apoptosis of cancer cells." (PMID 28068409, 2017). "In addition, it has been well documented that overexpression of Oct4 leads to tumorigenicity in different types of cancer, separately or together with Sox2 and Nanog." (PMID 28423536, 2017). "In addition, stemness factors including Nanog, Sox2, Oct4, and Bmi1 are highly expressed in cancer cells and have cancer stem cell properties." (PMID 27189061, 2016). "We identified SOX2 as a direct transcriptional target of KDM2A to promote cancer stemness." (PMID 27029061, 2016). "To test whether the formed spheres are cancer stem cells, we detected the expression of stemness genes, Oct-4, Sox-2, and Nanog, in NCI-H1299 and 95-D sphere cells and regularly cultured cells." (PMID 27556038, 2016).
cancer (continued). "Interestingly, cerivastatin but not pravastatin treatment of PA-TU-8902 cells significantly decreased the expression of SPP1 and SOX2, factors with important role in cancer metastasis and aggressiveness." (PMID 27175805, 2016). "Researchers were able to demonstrate that the transcription factor sex determining region Y-box 2 (Sox2) could maintain cancer stem cells in these cancers." (PMID 27240404, 2016). "Co-overexpression of Sox2 and Oct4 rescued the repression effect of miR-145 on cancer stemness." (PMID 27557511, 2016). "miR-126-3p inhibits cancer growth via directly targeting Sox2 and various other genes." (PMID 27191494, 2016). "Moreover, the genetic ablation of NAG-1 suppressed the expression of cancer stemness biomarkers including SOX2, OCT4, and CD44." (PMID 27708225, 2016). "Together, the phenotype seen in Caco2-SOX2 cells suggests that SOX2 might induce a cancer stem cell state in CRC leading to increased aggressiveness and poorer patient prognosis." (PMID 27411517, 2016). "Furthermore, Sox2 has been found to correlate with a worse prognosis in cancer patients, including those with BC." (PMID 26683522, 2016). "It has been reported that the growth and metastasis of certain cancer cells were suppressed when Sox2 was down regulated suggesting Sox2 may be a potential target for cancer treatment." (PMID 27371094, 2016). "In the present study, we bioinformatically identified highly consensus downstream genes regulated by SOX2 in lung SCC cells by combining previously-reported SOX2 downstream/correlated genes in multiple cancer cell lines with two RNA-seq datasets from 178 lung SCC specimens and 105 NSCLC cell lines." (PMID 26846300, 2016). "However, SOX2 positive cells were found to display several characteristics of cancer stem cells, as well as a decreased expression of the intestinal epithelial marker CDX2." (PMID 27411517, 2016). "YY1 shares many properties with cancer stem cells (CSCs) that drive tumorigenesis, metastasis and drug resistance and are regulated by overexpression of certain transcription factors, including SOX2, OCT4 (POU5F1), BMI1 and NANOG." (PMID 27225481, 2016). "Transcription factors such as Oct4, Sox2 and Nanog are required to maintain pluripotency and self-renewal capacity of cancer stem cells and play an important role in the uncontrolled proliferation of cancer cells." (PMID 27340862, 2016). "In line with this hypothesis, cancer cells expressing SOX2 showed an increased expression of the stem cell markers CD24 and CD44." (PMID 27411517, 2016). "In addition, sphere formation ability and expression of the cancer stem-like cell proteins, Sox2, and Oct4 were upregulated by recombinant IL-4 and downregulated by anti-IL-4 antibody in A498 cells, similar to the phenomena exhibited by MDA-MB-231 cells." (PMID 27895317, 2016). "Immunofluorescence analysis demonstrated the presence of de-differentiated NESTIN+ and SOX2+ cancer cell populations as well as oligodendrocytes (O4), astrocytes (GFAP) and neurons (TUJ-1) confirming the in vivo differentiation potential of the generated GTIC-like cells." (PMID 26899176, 2016). "Oct4 and Sox2 are both key transcription factors required for maintaining the pluripotency of stem cells, and these play crucial roles in the self-renewal of stem-like cells, as well as carcinogenesis and the development of some cancer types." (PMID 26769843, 2016). "Our present data showed that the hybrids highly expressed stemness genes such as Oct4, Sox2, Nanog and Lin28 compared to the parental cells, indicating that the hybrids may acquire cancer stem cell properties after cell fusion." (PMID 26498753, 2015). "The oncogenic role of SOX2 has been described in stem-like cells of various cancers." (PMID 26452033, 2015).